CD4 (CD4 molecule)
Diseases named in the same sentence as CD4 in open-access papers (continued):
Sharing a sentence is not in itself a finding about the gene and the disease.
AIDS (continued). "Patients with a CD4+ T-cell count of 200–350 cells/mm3 or greater than 350 cells/mm3 were less likely to develop AIDS following HIV diagnosis than were those patients without HAART treatment (HR = 0.225, 0.168, P < 0.001)." (PMID 26413133, 2015). "Clinical AIDS at ART initiation (adjusted hazard ratio (HR)=1.65; 95% CI 1.47–1.87), lower CD4 (adjusted HR=1.95 for 50 vs. 350 cells/μL; 95% CI 1.63–2.32) and older age (adjusted HR=1.47 for 50 vs. 30 years; 95% CI 1.29–1.69) were all associated with higher rates of mortality." (PMID 26165322, 2015). "After controlling confounding factors and interaction effect of the variables using backward stepwise regression, history of eye problem, CD4 count, and visual acuity of the eye remained statistically significant predictors of HIV/AIDS related ocular manifestation among HIV/AIDS patients." (PMID 26000175, 2015). "With realistic gaps in care (e.g. poor retention leading to ART resistance), projections of 20-year outcomes with delayed ART initiation (CD4 ≤350 cells/mm3) rose to 1,285,000 new HIV infections (95% UR 876,000–2,114,000) and 973,000 AIDS-related deaths (95% UR 679,000–1,412,000)." (PMID 26434780, 2015). "Virological success was defined as VL<50 copies/ml, immunological success as a confirmed increase of at least 100 CD4 cells/mm3 measured twice at least one month apart, and clinical failure as hospitalization for a non-AIDS event, an AIDS event, or death." (PMID 26714012, 2015). "One limitation of our study was the lack of any patient with CD4+ <200 or in the progressive stage of AIDS; therefore, we cannot evaluate oral lesions in these patients." (PMID 25745611, 2015). "A profiling study identified 62 differentially regulated miRNAs from the peripheral blood mononuclear cells (PBMCs) of HIV/AIDS patients with different CD4 counts and viral loads." (PMID 24828336, 2014). "Antiretroviral therapy, ART, especially when CD4+ cells are not yet depleted, can reduce viremia and slow its progression to AIDS." (PMID 24579041, 2014). "The impact of immune restoration has been clearly demonstrated in cohort studies and randomized clinical trials that have shown decreased mortality and morbidity, including AIDS defining clinical events and tuberculosis, with initiation of ART at higher CD4 counts." (PMID 25330196, 2014). "Once hospitalised, these patients have a high frequency of poor treatment outcome and mortality that appears to be driven by severity of illness, HIV/AIDS and no use of antiretroviral therapy if CD4 cell count is below 200 cells/μl." (PMID 24608875, 2014). "Our observations suggest that long-term restoration and preservation of high CD4 cell counts as a result of cART access is highly and durably effective in preventing AIDS as well as non-AIDS severe morbid events." (PMID 24885790, 2014). "More recently, a rare population of HIV infected individuals has been described who do not progress to AIDS and maintain high CD4+ T cell counts despite high levels of virus replication for many years (Viremic Non-Progressors, VNPs)." (PMID 25167059, 2014). "The outcomes were stop or switch of the third component, viral load (VL) <500 copies/ml, an increase of at least 100 CD4 cells/mm3, AIDS-defining event and non-AIDS-defining hospitalization or death." (PMID 25261780, 2014). "The RR of developing pre-specified non-AIDS events for ID vs. non-ID was 1.96 (95% CI 1.37–2.81, p<0.001) in unadjusted analysis and 1.43 (0.94–2.17, p = 0.095) after controlling for current CD4 count." (PMID 24498036, 2014). "At the time of the study, patients not yet eligible for ART (CD4 > 200 cells/mm3 and no clinical symptoms of AIDS) would be advised to attend every 6 months for a clinical assessment and CD4 count monitoring." (PMID 25134822, 2014).
AIDS (continued). "Patients in EuroSIDA starting at least 1 new antiretroviral drug with CD4<350 cells/μl and viral load (VL)>500 copies/mL were followed-up from the first day of VL< = 50 copies/ml until a new fatal/non-fatal non-AIDS/AIDS event." (PMID 24498036, 2014). "There was a persistent role of CD4 count at baseline and at 12 months in predicting AIDS, non-AIDS infection, and non-AIDS malignancy deaths." (PMID 24771333, 2014). "Few aspergillosis cardiac locations have been described in severely immunocompromised AIDS patients with less than 200 CD4 T-lymphocytes/μL, but no cardiac abscess has been related after solid transplantation." (PMID 24707433, 2014). "Low CD-4 count and advanced HIV/AIDS stages reflect the chronicity (prolonged existence) of the disease; therefore another cause of anaemia could also be the state of chronic illnesses." (PMID 24761799, 2014). "By using a combined definition of late ART initiation that included prior AIDS diagnoses, we were able to include patients who did not have available CD4 tests at ART initiation into the analysis." (PMID 24598459, 2014). "HIV is typically characterised by a period of viral replication and CD4 cell decline leading to AIDS and death in the absence of antiretroviral therapy (ART)." (PMID 24489776, 2014). "European Consensus definition group identify as late presentation (LP) persons, presenting for care, with a CD4 count below 350 cell/mm3 or presenting with AIDS-defining event, regardless of CD4 cell count." (PMID 25397438, 2014). "The European AIDS Clinical Society (EACS) guidelines have recommended ART initiation for patients with AIDS-defining illnesses, patients with HIV-related symptoms and asymptomatic HIV-positive patients with CD4 cell counts <350 cells/mm3." (PMID 24598459, 2014). "When evaluating these and other factors in the multivariable model, unemployment, CD4 count <200 cells/μL, HIV viral load >100,000 copies/mL, presence of clinical AIDS and white blood cell count <4,000 cells/μL, were independently associated with augmented odds of anemia." (PMID 25005803, 2014). "It is likely that variables not reported by viral loads strata (previous AIDS events, CD4 lymphocyte count, adherence, co-infection with viral hepatitis) can partly explain the differences seen between high and low viral load strata." (PMID 24830290, 2014). "The CD4 count and WHO stage are basic laboratory indicators of the progression of HIV/AIDS." (PMID 25360785, 2014). "The Cox proportional hazards model revealed that after controlling for age, sex, BMI, CD4 cell count, HIV viral load, clinical AIDS, and antiretroviral treatment, having anemia at enrollment increased significantly the one-year mortality risk of these HIV-infected patients." (PMID 25005803, 2014). "Overall, our study shows that lower CD4 cell counts led to a higher incidence rate of both AIDS-related and non-AIDS-related events." (PMID 24885790, 2014). "On the other hand, natural simian hosts preserve T lymphocyte populations despite high viremia and show attenuated immune activation that favors the maintenance of CD4+ T cells; hence, SMs do not develop AIDS." (PMID 25228901, 2014). "Although HIV preferentially infects CD4+ T cells and macrophages, efficient binding and infection of pDCs by HIV have been demonstrated and may contribute to AIDS pathogenesis." (PMID 25228901, 2014). "More specifically, it was previously shown, that those with a current CD4 count of <200 cells/μl and with suppressed viraemia on cART have lower rates of AIDS and, to a lesser extent, non-AIDS events compared to patients with ongoing viral replication." (PMID 24498036, 2014). "We demonstrated a positive correlation of TMtb-iNet with CD4+ and CD8+ T cells from PTB patients or AIDS patients (acute and chronic forms of HIV infection), forming a transcriptome bridge of similarity (i.e., an interferon-related process) between these two diseases." (PMID 25371902, 2014).
AIDS (continued). "The critical role of CD4+ T cell help in antigen-specific CD8+ T lymphocyte and general immune function is well illustrated by the sequelae suffered by patients suffering from AIDS." (PMID 25119341, 2014). "The control cohort included 56 HIV-positive patients without lymphoma (mean age: 44 ± 9 years) selected to be matched for the CD4+ lymphocyte count with the AIDS-RL: among this population, 9 patients [16%] were not treated by HAART." (PMID 25908934, 2014). "The majority of measurements came from patients located in the Northeast (94.4%); 87.4% of patients had no comorbid conditions, and 7.7% had experienced an AIDS-defining event prior to their CD4 measurement." (PMID 24866200, 2014). "Local people living with HIV/AIDS (PLHA) covered with follow-up care, tested for CD4, initiated and retained antiretroviral therapy (ART), before and after the task shifting from government health facilities to community-based organizations (CBOs), 2008 to 2012, Nanjing, China." (PMID 25050797, 2014). "Among people diagnosed with HIV since 2005 in Armenia, 62.8% of people with AIDS or a low CD4 count had not received ART by the end of 2010." (PMID 25095830, 2014). "This issue was nicely illustrated by the SMART and ESPRIT studies in which substantially more non-AIDS events than AIDS events were observed; most non-AIDS events were not correlated with CD4 and HIV-1 RNA levels." (PMID 24667813, 2014). "One interesting observation in this study was that DTH normalization occurred in approximately 60% of anergic participants regardless of pre-HAART CD4 cell count and prior AIDS diagnoses." (PMID 24499779, 2014). "Elevated circulating lipopolysaccharide (LPS), which is correlated with depletion of CD4 cells during chronic HIV infection and AIDS, may also reduce miR-150 levels in leukocytes." (PMID 24828336, 2014). "Immunologic non-responders (patients who maintain a lower peripheral CD4+ T-cell counts despite sustained suppression of plasma HIV viremia) remain at higher risk for both AIDS and non-AIDS clinical events." (PMID 24497828, 2014). "Although SIVΔvpx-infected animals had prolonged survival, they did eventually succumb to AIDS with CD4 decline despite the fact that there was little to no infection of macrophages." (PMID 24465411, 2014). "CD4-cell count, viral load and AIDS at presentation were not significantly different between subtypes." (PMID 25397433, 2014). "Several cohort studies have shown that initiation of ART when the CD4 T-cell count is between 350 and 500/mm3, rather than <350/mm3, is beneficial in terms of mortality and/or progression to AIDS." (PMID 24942364, 2014). "The persistent role of lower CD4 counts and lack of viral suppression in predicting both AIDS and non-AIDS death after the first year of ART emphasizes the importance of maintaining adherence to therapy and ensuring patients are switched from failing regimens." (PMID 24771333, 2014). "We assumed that people who did not have a CD4 count did not have AIDS since if they had severe disease, they would have been diagnosed with AIDS." (PMID 24223724, 2013). "None of the other parameters, including AIDS diagnosis, proportion of treatment naïve patients and mean Nadir CD4 T-cell counts, were significantly different across samples." (PMID 23349927, 2013). "Histopathological examinations indicated that the absence of CD4-positive T lymphocytes the decreasing function of antigen-presenting activity in macrophages of patients with AIDS, and a large number of yeasts in the septal capillaries were observed." (PMID 24058271, 2013). "Conversely, assuming that those without a CD4 count and without AIDS were not late presenters lowered the proportion of late presenters to 45.1% overall (46,242/102,532) and to 26.0% in Eastern Europe (627/2,413)." (PMID 24137103, 2013).
AIDS (continued). "We aim at memory CD4 T-cells, utilizing the stem cell properties of these cells to reprogram an anti-HIV memory repertoire to eliminate the viral reservoir, toward achieving an AIDS-free world." (PMID 24151495, 2013). "We found that patients in the AIDS progression group had higher HIV-1 viral loads and lower CD4 cell counts than did patients in the AIDS non-progression group." (PMID 23874430, 2013). "In contrast, the seven viremic HIV-2-infected individuals, named non-controllers (NCs), generally had low CD4 counts (<240/μl) and most of them suffered from end stage AIDS at the time of virus isolation." (PMID 23497283, 2013). "Though ocular manifestations of HIV/AIDS are low, HIV/AIDS patients especially those with lower CD4+ T cell count and older patients should have eye checkup and follow up by an ophthalmologist; and there should be concerted care with a multidisciplinary approach." (PMID 23710936, 2013). "In the univariate analyses, sex, age at diagnosis, transmission categories, marital status, educational level, CD4+ T-cell count within 6 months at diagnosis, concurrent HIV/AIDS diagnosis, and HAART were statistically significant associated with death events (P<0.05 for all)." (PMID 24376638, 2013). "In China, a CD4 cell count ≤ 350 cells/μL is recommended as a criterion (regardless of WHO clinical stage of HIV/AIDS) for medical eligibility for the initiation of antiretroviral therapy among PLWHA." (PMID 24289721, 2013). "The univariate analysis demonstrated that factors, including age at diagnosis, transmission categories, marital status, educational level, CD4+ T-cell count within 6 months at diagnosis, concurrent HIV/AIDS diagnosis, and HAART, had significant influence on AIDS survival." (PMID 24376638, 2013). "In conclusion, MAC peritonitis should be considered in patients presenting with non-specific abdominal symptoms in the setting of AIDS and low CD4 count." (PMID 24303220, 2013). "Patients in hospital-associated settings showed a higher proportion of CDC stage of AIDS, a lower CD4 cell count, and a higher frequency of non-B HIV-1 subtype." (PMID 24262206, 2013). "The median CD4 cell count was 380.0 per 100 cells/μL (IQR: 220.0–510.0); the median viral load was 2.6 log10 copies/mL (IQR: 2.6–3.7); 63 (24.8%) were diagnosed with AIDS; and 123 (48.4%) were ≥95% adherent to ART in the 12 months preceding enrollment." (PMID 23723968, 2013). "However, other T-cell markers such as the percentage of CD4+ T-cells and the CD4:CD8 ratio have also been shown to predict AIDS and non-AIDS related morbidities." (PMID 24204912, 2013). "This also indicates the need for regular ophthalmic evaluation of all patients with HIV/AIDS irrespective of CD4 counts as ocular lesions are noted in spite of HAART." (PMID 23514612, 2013). "LTFU tended to be non-Japanese, younger age, had higher CD4 count, and less likely to have a history of AIDS, on ART, and covered by health insurance/public assistance, compared to the patients who continued to visit the clinic." (PMID 23951307, 2013). "However, differential survival after AIDS diagnosis arose among age at diagnosis, transmission categories, educational level, CD4+ T-cell counts within 6 months at diagnosis (cell/μL), concurrent HIV/AIDS diagnosis and receiving HAART." (PMID 24376638, 2013). "After controlling for age, sex, race, CD4 and VL at HAART initiation, prior AIDS, Hepatitis B and C, prior ARV usage and regimen, the 12-year survival rates between the cohorts decreased from a 21.5% crude difference (NHS–91.5%; HAVACS–70.0%) to a 1.6% adjusted difference (NHS–98.7%; HAVACS–97.1%)." (PMID 23658717, 2013). "The HIV specific effector cells, specifically memory CD4 T-cells, play decisive roles not only in anti-HIV immunity but also in AIDS pathogenesis, since these cells govern functions of both CD8-cells and B-cells, regulate both cellular and humoral immunities, thereby determine the prognosis of AIDS." (PMID 24151495, 2013).
AIDS (continued). "Development of CD4 cell count from 9 to 48 months after seroconversion was analyzed using a mixed-effects model and 2 models that jointly modeled CD4 cell counts and time to censoring event (start ART, <100 CD4 cells/mm3, or AIDS) among therapy-naïve MSM HIV-1 seroconverters in the Netherlands." (PMID 23724048, 2013). "Compared to subtype A cases, A/D recombinants cases had a significant faster disease progression to AIDS, but the progression to CD4 cell counts ≤250 cells/mm3 and death was not significantly faster." (PMID 23951241, 2013). "Of note, CD4 counts at interruption in both SMART and DART trials were lower than in PENTA 11; however, although DART patients had late stage HIV disease, it is also true that 26 % of children in PENTA 11 had experienced an AIDS event prior to entry." (PMID 22584916, 2013). "Our study did not include patients who had started ART, or had a CD4 cell count below 100 cells/mm3 within 9 months or AIDS within 21 months after seroconversion." (PMID 23724048, 2013). "Of that sum, fifty seven patients (40.7%) were excluded from HAART, because they had CD4 count ≥350 cells/ mm3 and or were without any AIDS-defining illness and eighty three patients (59.3%) qualified for initiation of first line HAART." (PMID 24198891, 2013). "In Uganda, an AIDS diagnosis is an independent ART eligibility criterion, while the CD4 cell count threshold for ART eligibility has changed from equal to or less than 200 cell/mm3 at the start of ART roll out in 2004 to equal to or less than 250 cells/mm3 in 2008." (PMID 23951241, 2013). "MAC peritonitis should be considered in a patient presenting with nonspecific abdominal symptoms in the setting of AIDS and low CD4 count." (PMID 24303220, 2013). "Although the CD4 count is an important factor in deciding whether to initiate ART in asymptomatic patients and assessing AIDS progression in PLHIV, accurate ART assessment cannot be conducted without data on plasma VL." (PMID 24086744, 2013). "CD4 T-cell count changes at 6 and 12months for non-AIDS and AIDS patients on different first-line regimens." (PMID 23118869, 2012). "Adverse prognostic factors for ARL included a CD4+ count of less than 100 cells/μL, age older than 35, history of injection drug use, poor performance status, elevated serum lactate dehydrogenase (LDH), advanced stage of disease, and prior AIDS diagnosis." (PMID 22400030, 2012). "During MTB infection the activated macrophages (MA) rise rapidly to a level of about 40, somewhat below MR, and then decline during AIDS because the lack of CD4+ T cells reduces macrophage activation." (PMID 23209581, 2012). "There was no observed evidence of changes in mortality associated with age relative to the general population after controlling for time updated incidence of prior AIDS, mode of HIV exposure, time updated CD4 cell count, time updated viral load and time updated regimen number." (PMID 23144991, 2012). "Since the announcement of World Health Organization recommendation and guidelines for initiation of antiretroviral Treatment at CD4 count below 350, many developing countries are adopting this strategy in their country specific guidelines to care and treatment of HIV and AIDS." (PMID 23077701, 2012). "Furthermore, the few human subjects who develop AIDS among HIV-1 positive elite controllers (with undetectable plasma HIV RNA levels) have abnormally high T cell activation which is thought to contribute to their progressive CD4 T cell loss in the absence of viraemia." (PMID 22970212, 2012). "The high plasma viral RNA load, PBMC proviral DNA load and decreasing CD4+ T-cell counts before the development of AIDS, indicated a lack of viral control by K03135 host responses." (PMID 22427893, 2012). "Despite differences in CD4 cell count evolution, death and non-TB AIDS rates were similar across study groups." (PMID 22412867, 2012).